TLR8 (toll like receptor 8)
Diseases named in the same sentence as TLR8 in open-access papers (continued):
Sharing a sentence is not in itself a finding about the gene and the disease.
lupus (continued). "Here, we analyzed the role of human TLR8 in a mouse lupus model expressing a human TLR8 BAC transgene (huTLR8tg) that confers low-level huTLR8 expression, insufficient to cause spontaneous inflammation in non-autoimmune mice." (PMID 37495396, 2023). "In contrast, the association between clinical manifestations and TLR7, TLR8 and TLR9 polymorphisms is clear and the involvement of the endosomal TLRs, mainly TLR7, in lupus is backed up by several studies." (PMID 34572504, 2021). "Low expression of TLR9 due to single nucleotide polymorphisms would increase SLE susceptibility in humans, and deletion of TLR8 and TLR9 would accelerate lupus development in mice." (PMID 35126357, 2021). "TLR8 is also present in humans and TLR8 expression levels are upregulated in blood cells of paediatric and adult lupus patients." (PMID 29650017, 2018). "While TLR7 promotes cDC activation in lupus, TLR8 downregulates TLR7 expression and TLR7-dependent cDC activation." (PMID 27034965, 2016). "The high level of TLR8 in B cells from lupus-prone 564Igi mice is directly related to ANAs production and contributed to the lupus-like pathogenesis in female 564Igi mice." (PMID 26068236, 2015). "TLR7 and TLR8 have already been shown to play a central role for the recognition of self RNA in the immunopathogenesis of autoimmune diseases such as systemic lupus erythematosus (SLE), psoriasis, rheumatoid arthritis, Sjögren's syndrome and others." (PMID 24904837, 2014). "For example, systemic lupus erythematosus was found to be associated with variation in TLR7 and Crohn’s disease and ulcerative colitis with variation in TLR8." (PMID 22857391, 2012). "In addition, autoantibodies that are common to both lupus and SD, specifically anti-SSA (Ro), anti-SSB (La), and anti-RNA, were diminished in the double-knockout mice as compared to Tlr8-deficient animals." (PMID 39310226, 2024). "Moreover, TLR8−/− TLR7−/− mice show ameliorated lupus pathogenesis as well as restored MZ B cell population, indicating a critical function of TLR8 in controlling TLR7 activation." (PMID 26068236, 2015). "Moreover, BMS-986256 (Afimetoran) is another small molecule that blocks TLR7 and TLR8, can be delivered orally and was able to prevent lupus symptoms in animals treated before the onset of disease as well as reverse organ damage when given after symptoms had already started." (PMID 36389822, 2022). "Mammalian endosomal TLRs, specifically TLR7, TLR8, TLR9 and TLR3, are crucial in the development of systemic lupus erythematosus (SLE) in humans." (PMID 40976999, 2025). "Endosomal toll-like receptors (TLRs) TLR7, TLR8, and TLR9 play an important role in systemic lupus erythematosus (SLE) pathogenesis." (PMID 39858436, 2025). "Furthermore, SNPs in TIRAP are associated to the incidence and severity of several diseases, such as tuberculosis, HIV, and systemic lupus erythematosus (SLE) as well as infections/diseases in which TLR8 is likely to play a role." (PMID 35884781, 2022). "Moreover, TLR8 deletion in the Nba2.Yaa lupus prone mice accelerates SLE due to increased TLR7 responses." (PMID 36389822, 2022). "TLR8 knockout mice have high endogenous TLR7 expression and activity that promotes a lupus-like phenotype." (PMID 35874527, 2022). "Various oligonucleotides that mimic TLR ligands (for TLR7, TLR8, TLR9) have been synthesized and are prospective therapeutics for lupus." (PMID 34572504, 2021). "We demonstrated previously that in vivo TLR8 restrains TLR7 on DCs, and that TLR8ko mice on the C57BL/6 background develop spontaneous lupus due to increased TLR7 signaling by DCs, while TLR8ko B cells or macrophages retain normal TLR7 signaling." (PMID 34108972, 2021). "Several lines of evidence have revealed inappropriate activations of TLR7, TLR8, and TLR9 in systemic lupus erythematosus (SLE) and several other autoimmune diseases." (PMID 28061847, 2017).
lupus (continued). "Antimalarial drugs such as hydroxychloroquine which act as a TLR7, TLR8 and TLR9 antagonist are used for the treatments of rheumatoid arthritis and systemic lupus erythematosus." (PMID 26226614, 2015). "Even though it does not appear to have a ligand, research has shown that TLR8 in mice regulates TLR7‐mediated lupus, which indicates that it is physiologically significant." (PMID 40976999, 2025). "In concerted with such hypothesis, a very recent study reported that TLR8 impaired the nursing capacity of EBI macrophage and resulted in the compromised erythropoiesis in systemic lupus erythematosus prone mice carrying human TLR837." (PMID 38971858, 2024). "It is also possible that the lesions in the huTLR7/8 BAC mice are distinct from those seen in lupus prone strains of mice with Tlr7 overexpression or in humanized TLR8 mice because they result from a neoplastic rather than an inflammatory process." (PMID 25229618, 2014). "Similar to TLR7, both TLR8 and TASL are involved in the etiology of systemic lupus erythematosus (SLE), a female-biased autoimmune disease." (PMID 34858409, 2021). "Indeed, TLR8-deficient mice on the C57BL/6 background, which is not prone to lupus, develop SLE due to increased TLR7 expression and signaling by cDCs and pDCs." (PMID 36389822, 2022). "Despite the fact that murine TLR8 does not seem to have a ligand, we previously demonstrated that it plays an important biological role by controlling TLR7-mediated lupus." (PMID 31552019, 2019). "Both TLR8−/− and TLR8−/− TLR9−/− mice could develop lupus phenotype by lacking their inhibitory effects on TLR7 signal." (PMID 26068236, 2015).
autoimmune disease (33 papers, 2014 to 2025). A disorder resulting from loss of function or tissue destruction of an organ or multiple organs, arising from humoral or cellular immune responses of the individual to their own tissue constituents. "This has implications for antiviral and antibacterial responses, as well as susceptibility to inflammatory and autoimmune diseases, highlighting TLR8’s role in immune regulation and disease vulnerability." (PMID 39475881, 2024). "Previous studies demonstrated that TLR8 is involved in inflammatory dermatosis and autoimmune diseases, which is in the upstream of NF-κB-NLRP3 and associated with the production of IL-1β, interferon (IFN)-α, and IL-645–48." (PMID 38321132, 2024). "The involvement of Toll-like Receptors (TLR) in the recognition of self-molecules is established for the RNA-sensing receptors of innate immunity, TLR7 and TLR8, which enhanced expression is directly linked to the pathogenesis of autoimmune diseases." (PMID 33498655, 2021). "Toll-like receptor 8 (TLR-8) plays a role in the pathogenesis of autoimmune disorders and associated gastrointestinal symptoms that reduce quality of life of patients." (PMID 32477333, 2020). "Interestingly, in a human setting, a mutation in TLR8 was recently described and found to cause severe autoimmune disease in the monozygotic twins who carried it." (PMID 38791389, 2024). "The identification of patients with coding variants in TLR7 and TLR8 has established the relevance of dysregulation of these receptors for human autoimmune disease, but equivalent coding variants in UNC93B1 that alter TLR responses to self-nucleic acids have not yet been described." (PMID 38780621, 2024). "If TLR8 regulates TLR7 expression upstream of TLR7 in humans, the association of TLR8 with autoimmune disease pathogenesis may have been underestimated and should be investigated." (PMID 39544932, 2024). "Because most autoimmune diseases are more prevalent in females, it has been postulated that elevated levels of TLR8, as an X-linked gene, might play a direct role in the pathogenesis of these diseases, including SSc." (PMID 28245863, 2017). "It is thus hypothesised that in some autoimmune diseases deficiency of either TLR8 or TLR9 will result in decreased competition of these endosomal TLRs to bind to Unc93B1, making TLR7 more available and resulting in higher TLR7 trafficking and response." (PMID 28553556, 2017). "Co-dependent transcription from the active X chromosome and escape from XCI could both contribute to higher TLR8 protein abundance in female cells, which may have implications for the response to viruses and bacteria, and the risk of developing inflammatory and autoimmune diseases." (PMID 37723501, 2023). "TLR7 and TLR8 have gained significant attention due to their role as potential therapeutic targets in autoimmune diseases, vaccination adjuvants and targeted immunotherapy in cancer." (PMID 41322409, 2025). "This is demonstrated by the fact that knocking out either Tlr8 or Tlr9 in healthy C57BL/6 mice induced SLE-like autoimmune disease, while additional knockout of Tlr7 eliminated disease symptoms, indicating that the disease development was dependent on TLR7." (PMID 38791389, 2024). "The results showed that both the proportion and density of TLR8+ macrophages in SjD tissues were significantly higher than those in CS tissues, indicating a specific role of TLR8 in autoimmune diseases, such as SjD." (PMID 39544932, 2024). "Meanwhile, many studies have revealed that the expression levels of TLR7 and TLR8 are altered in some autoimmune diseases, such as arthritis, cancers, or in antiviral regimes, including coronavirus and human immunodeficiency virus(HIV) prevention." (PMID 36476317, 2022). "Mice expressing human TLR8 show an increased frequency of autoimmune disorders, which supports the general importance of TLR8 in autoimmune diseases." (PMID 32033104, 2020).
autoimmune disease (continued). "TLR-8 specifically plays a role in autoimmune disorders because it is involved in the regulation of TLR-7 and TLR-9 signaling and a direct link has been found between the dysregulation of TLR-8 activation and pathological inflammation." (PMID 32477333, 2020). "Inhibition of endosomal TLR-8 signaling is a possible approach to modulate the immune response in autoimmune diseases as shown for CQN." (PMID 32477333, 2020). "Inhibition of endosomal TLRs, such as TLR-8 has great therapeutic potential for the treatment of autoimmune diseases as shown for the TLR7/8/9 antagonist chloroquine (CQN)." (PMID 32477333, 2020). "The dysregulation or overexpression of TLR-8 has been found to contribute to the pathogenesis and progression of autoimmune disorders, such as rheumatoid arthritis, systemic sclerosis, and inflammatory bowel disease." (PMID 32477333, 2020). "Inhibitors of PI3Kδ have been approved for treatment of cancer, inflammatory and autoimmune diseases, and our data provide rationale to further explore the targeting of the PI3Kδ-TLR8 axis in SSc-PF and IPF, via repurposing drugs used for cancer treatment." (PMID 32210969, 2020). "This constitutes a novel mechanism by which endosomal TLR-8 senses host miRNAs resulting in the release of pro-inflammatory cytokines and thus potentially contributing to autoimmune disorders." (PMID 31867014, 2019). "The possible role of TLR8 in autoimmune diseases has been recently considered, since together with TLR7 it is one of the two TLRs expressed on the X chromosome." (PMID 28245863, 2017). "Accumulating evidence suggests important functions for human Toll-like receptor 8 in vivo in tuberculosis and autoimmune diseases." (PMID 29416532, 2017). "There is increasing evidence indicating that some endogenous ligands can activate TLR7 and TLR8 and result in autoimmune disease in mouse models." (PMID 25514371, 2014). "TLR8 and 9 are believed to be involved in the development of some autoimmune diseases such as rheumatoid arthritis." (PMID 25514371, 2014). "VentiRx Pharmaceuticals is also developing a TLR8 specific antagonist for the treatment of autoimmune diseases; VTX-763 is a preclinical lead which shows marked inhibition of TLR8-induced NF-κB activation and TNF production in vitro." (PMID 24474949, 2014). "Furthermore, inhibitors of the CU—CPT series targeting TLR8 impede signaling pathways by stabilizing TLR8 dimers, which verifies their therapeutic potential for autoimmune diseases in transgenic mice." (PMID 40877572, 2025). "Endosomal Toll-like receptors (TLRs, including TLR3, TLR7, TLR8 and TLR9) play crucial roles in immune responses by recognizing pathogen-associated molecular patterns; however, their aberrant activation is implicated in inflammatory and autoimmune diseases." (PMID 40887497, 2025). "Similarly, in patients with SSc, pDCs show elevated TLR8 expression and increased type I IFN activity, further supporting the association between TLR8 dysregulation and autoimmune disease progression." (PMID 39731171, 2024). "The TLR8 gene, located on Xq24, is another X-linked gene known to escape XCI, contributing to significant sex differences in immune responses and disease susceptibility, including autoimmune disorders and cancers." (PMID 39731171, 2024). "Increases in TLR7 or TLR8 gene copy number can induce autoimmune disease in mice, and failures in X chromosome inactivation, where TLR7 and TLR8 are located, have been proposed as a cause of SLE in humans." (PMID 38780621, 2024). "The most notable feature of X-linked genes affected by Xist perturbation is the high number of genes involved in innate immune response (TLR7, TLR8, TLR13, TASL, and CXCR3), which have been reported to be associated with or to have a causative role in different autoimmune diseases." (PMID 38701219, 2024). "The role of TLR-8 in autoimmune disease is yet to be fully explored." (PMID 31867014, 2019).
autoimmune disease (continued). "Illness may be caused by constitutive activation of human TLR7 or TLR8 in the bacterial artificial chromosome positive mice as increased TLR7 and TLR8 expression or activation has previously been implicated in autoimmune disease." (PMID 25229618, 2014). "In addition, accumulating evidence suggests that TLR8 contributes to autoimmune diseases as well." (PMID 35309296, 2022). "We used mice that were double-knockouts for TLR7 and TLR8 (TLR7/8 KO) to test the hypothesis that a dual antagonist of these receptors could protect from PD degeneration seen as autoimmunity disease, reducing the production of lymphocytes directed against DA neurons." (PMID 33317145, 2020). "Its involvement in autoimmune diseases like SLE and SSc, along with its impact on tumor immunity, highlights TLR8 as a promising target for developing sex-specific therapies." (PMID 39731171, 2024). "Recent research has further demonstrated that inhibitors like TAC5 can selectively target endosomal TLRs (TLR3, TLR7, TLR8, and TLR9) to modulate immune responses and potentially treat autoimmune diseases like psoriasis and systemic lupus erythematosus." (PMID 38732254, 2024). "Recent evidence suggests that TLR-8 also senses host microRNAs (miRNAs) and implicate TLR-8 in autoimmune disorders." (PMID 31867014, 2019). "Altogether, data uncover novel effects that type I IFN exerts in TLR8-activated neutrophils, which therefore enlarge our knowledge on the various biological actions which type I IFN orchestrates during infectious and autoimmune diseases." (PMID 26790609, 2016). "Given the implication of TLR7 in autoimmune diseases, it is interesting to speculate that an attenuation of TLR7 signaling was necessary, leaving TLR8 to emerge as the primary miRNA-sensing TLR in humans." (PMID 41322409, 2025). "Roles for TLR7, TLR8, and TLR9 in the pathology of such diseases are now well established in humans and mice, and suppression of TLR activation is being pursued therapeutically as a treatment for several autoimmune diseases." (PMID 38780621, 2024). "Likewise, intracellular nucleic-acid can also induce the production of IFN-beta via nuclei-acid sensors signaling pathways, including TLR7/TLR8-MyD88 signaling pathway, TLR3-IFN-beta signaling pathway and so on in autoimmune diseases." (PMID 36994418, 2023). "However, the dysregulation of TLR7, TLR8, and TLR9 plays a major role in numerous autoimmune diseases." (PMID 28553556, 2017). "Both TLR8 and TLR7 could contribute to the pathogenesis of autoimmune diseases." (PMID 33498655, 2021).
Autoimmunity (31 papers, 2013 to 2026). The occurrence of an immune reaction against the organism's own cells or tissues. "Crucially, rare TLR7 and TLR8 mutations at this antagonist binding site decrease inhibition by 2'-OMe guanosine RNA fragments, leading to autoimmunity in patients." (PMID 41667621, 2026). "Currently, while the connection with autoimmunity is enticing, the direct connection between variants in TLR8 and CSK is unproven." (PMID 35893065, 2022). "Several studies have shown that the expression of two copies of Tlr7 or Tlr8 alone was sufficient to induce autoimmunity in mice, whereas mice deficient in Tlr7 with a genetic background predisposing to lupus are significantly protected against autoimmunity." (PMID 33498655, 2021). "TLR8 deficiency leading to autoimmunity was also noted in mice." (PMID 34790205, 2021). "It has been reported that damaged TLR8 signaling pathway in MS could impair the production of IL-12, suggesting that TLR8 deficiency in MS may contribute to autoimmunity." (PMID 34790205, 2021). "TLR8 is furthermore implicated in the generation of autoimmunity." (PMID 33499143, 2021). "In addition, Tlr9- and Tlr8-double-deficient C57BL/6 mice develop spontaneous signs of autoimmunity such as splenomegaly, autoantibody production, and glomerulonephritis." (PMID 29650017, 2018). "Remarkably, dendritic cells of TLR8-deficient mice overexpressed Tlr7 and were hyperresponsive to TLR7 ligands, and the animals developed autoimmunity." (PMID 37723501, 2023). "Its role in the development of autoimmunity was established with the aid of murine models, where the expression of two copies of Tlr7 or Tlr8 was sufficient to induce lupus-like manifestations." (PMID 37723501, 2023). "Excess TLR7 or TLR8 activity, by contrast, can lead to sterile inflammation and autoimmunity, and is an important contributor to the pathogenesis of autoimmune syndromes." (PMID 37723501, 2023). "If the TLR8 signal is affecting CSK autoimmunity, it is likely that dominant inheritance is affecting the trait." (PMID 35893065, 2022). "Nevertheless, our studies on TLR8-deficient mice revealed that TLR8 has an important function on restraining TLR7 and protecting from autoimmunity." (PMID 36389822, 2022). "Several investigations showed that murine TLR8 plays a pivotal role in the regulation of myeloid cells and prevention of autoimmunity, by controlling TLR7 expression." (PMID 32854231, 2020). "For instance, Tlr7 expression is increased in Tlr8 null mice and these mice exhibit lupus-like autoimmunity due to increased levels of RNP-specific autoantibodies." (PMID 31684953, 2019). "Evidently, TLR9 and TLR8 inhibit TLR7-mediated autoimmunity and renal inflammation in a synergistic manner." (PMID 29650017, 2018). "generated TLR8-deficient mice through gene targeting and revealed that mouse TLR8 plays a pivotal role in the regulation of mouse TLR7 expression and the spontaneous autoimmunity." (PMID 39544932, 2024). "Overall, TLR8- or TLR9-deficiency decreases the competition with TLR7 for association with UNC93B1 and results to increased TLR7 trafficking and signaling that ultimately leads to autoimmunity." (PMID 36389822, 2022). "TLR3 appears to exist as a functional receptor on the cell membrane more frequently than other endosomal TLRs, probably because endogenous agonists of TLR7, TLR8, and TLR9 are more abundant than dsRNA in uninfected cells, and therefore surface localization of TLR3 poses a lower risk of autoimmunity." (PMID 33597952, 2020). "In humans, TLR8 senses ssRNA but its role in autoimmunity is less clear." (PMID 29650017, 2018). "It is striking that all single-stranded endosomal RNA sensors (i.e., TLR7, TLR8, and TLR13) are codified in the X chromosome, possibly explaining sex-biased autoimmunity due to defects in dosage compensation." (PMID 40334662, 2025).